CDKN2A (cyclin dependent kinase inhibitor 2A)
Diseases named in the same sentence as CDKN2A in open-access papers (continued):
Sharing a sentence is not in itself a finding about the gene and the disease.
tumor (continued). "Compared to cells in tumor 3 that expressed increased epithelial markers like CDKN2A, CRB3, KRT13, and KRT6, tumor cells in metastatic LN exhibited high expression of mesenchymal markers like CDH3, ECM1, TGFB1, WARS, and VIM, indicating that tumor metastasis was related to EMT." (PMID 36569924, 2022). "CDKN2A/BHDIFN‐IHD had shorter survival times than CDKN2A/BWT and downregulated immune response pathways, suggesting that poor prognosis in CDKN2A/BHD LUAD could potentially be attributed to an immunosuppressive tumor microenvironment owing to IFN‐I depletion." (PMID 35253368, 2022). "Following this line, by crossing to KC mice and analyzing transposon insertions in the resulting tumors, it has been described a large number of candidate genes that may promote tumor progression in KrasG12D initiated pancreatic tumors namely TGF-β and p16/CDKN2A." (PMID 34778259, 2021). "Importantly, using microdissected tumor samples and WGS, we detected the highest frequencies of homozygous deletions of the critical tumor suppressor genes CDKN2A, TGFBR2, TRAF3, and potential synthetic lethal target MTAP amongst NPC genomic reports thus far8–14." (PMID 34234122, 2021). "This detection of non-homogeneous deletions of CDKN2A suggests that besides the polyclonal origin, several genetic subclones might also exist within one tumor." (PMID 34277422, 2021). "Additionally, to sustain proliferative signalling (right side), the tumour oncogene CCND1, probably influenced by the co-expressed gene NCOA1/3 as well as the suppressors CDKN2A and CDKN2B, which govern the cell cycle, were genetically altered to enhance cancer cell growth in both smoking subgroups." (PMID 32455963, 2020). "Some tumours with wild type RB1 have shown to exhibit chromothripsis, where alternative mechanisms of RB1 deregulation, such as overexpression/amplification of cyclin D1 (CCD1) and/or inactivation of cyclin dependent kinase inhibitor 2A (CDKN2A), have been identified." (PMID 31619019, 2019).
tumor (continued). "Among the tumor-related genes, the top amplified genes included ERBB2 (17q21), MYC (8q24), GNAS (20q13), EGFR (7p11), ZNF217 (20q13), CCNE1(19q12), NCOA3 (20q13), and CDK6 (7q21), and the most frequently deleted genes were CDKN2A (9p21), CDKN2B (9p21), KIT (4q12), SMAD4 (18q21), and FGFR1 (8p12)." (PMID 31541076, 2019). "Therefore, even though maybe the RB pathway is not always aberrant at the genomic level (deletions of RB or p16/CDKN2A, amplifications of cyclins or CDKs), there is always E2F1 free owing to uncontrolled replication of tumor cells." (PMID 31138805, 2019). "Fourth, expression of activated BRAF V600E alone does not lead to tumor development in in vitro and in in vivo mouse models, while the combined activation of BRAF and loss of CDKN2A/B is transforming, suggesting that additional mutations to bypass senescence are required to advance to phase III." (PMID 29616301, 2018). "These detections of non-homogenous deletions of CDKN2A suggest that besides the polyclonal origin, several genetic subclones might also exist within one tumor." (PMID 29848954, 2018). "Yet, this group (35% of MIBC in the TCGA cohort), also comprises 41% of tumors with CDKN2A deep deletions, meaning that CDKN2Ahigh tumours, which do not show any homozygous deletion of CDKN2A, are in part not a representative, but a highly selected subgroup of basal squamous tumours." (PMID 30258198, 2018). "It was notable that cdkn2a/b and rb1 double somatic inactivation did not influence the overall tumor incidence rate, and merely lead to form the mixture of MPNSTs & MB-like PNETs in an each single tumor developing zebrafish." (PMID 28903419, 2017). "Moreover, other types of oncogenes such as products of Cdkn2a gene, p16lnk4a, and p19arf are also elevated in the absence of Wip1 and promote tumor suppression in mammary gland tumors." (PMID 28144241, 2017). "However, after infection with shRNA-Tsc2 + Cdkn2a lentiviruses none of these cells contributed to spheres or tumours, excluding that they are the cells of origin of our AML model." (PMID 29133867, 2017). "Whole-exome analysis of genomic DNA from both the tumor and blood indicated no somatic, non-synonymous coding mutations within the tumor, but a heterozygous, unique germline, loss of function mutation in CDKN2A (p16INK4A, D74A)." (PMID 27519597, 2016). "An important point is that, although all pancreatic cells in KIC mice express KrasG12D and have inactivated Cdkn2a (indeed, p48::Cre drove TdTomato expression throughout the pancreas), Rgs16::GFP is absent at P15 except for expression in the earliest lesions, and then throughout tumor progression." (PMID 26438693, 2015). "Indeed, wedelolactone could activate PRC2 downstream tumor suppression genes such as DAB2IP, ADRB2, CDKN2A and GADD45A, thus it serves as a mechanism for its inhibition on PRC2-dependent cancer cells." (PMID 25944687, 2015). "Separately, the effects of CDKN2A, a cell cycle control gene known to be a tumor suppressor, were not strong enough to reach genome-wide significance in the previous genome-wide studies of European Whites and therefore required a larger independent replication sample for final identification." (PMID 23836053, 2013). "PTEN and CDKN2A methylation levels were low and increased in late stage III and IV (p = 0.003, p = 0.004 between stage I and III, p = 0.018 and p = 0.003 between stage I and IV), while MGMT methylation levels were low and appear to decrease with tumor stage (p = 4.5e-4 between stage I and IV)." (PMID 24093668, 2013).
tumor (continued). "The non-negligible CDKN2A methylation of normal colorectal mucosa may confound the assessment of tumor-specific hypermethylation, suggesting that corresponding non-neoplastic tissue should be used as a control." (PMID 22925370, 2012). "Intriguingly, excluding CDKN2A, none of the genes implicated by these GWA scans have previously been evaluated in targeted association studies, emphasizing that the candidate gene approach was severely limited by inadequate knowledge of tumor biology." (PMID 21307401, 2010). "Unsupervised two-dimensional cluster analysis of the DNA methylation β-values revealed a distinct cluster of 11 tumor samples, the majority of which contained BRAFV600E and showed frequent DNA methylation of known CIMP-associated markers, including CDKN2A, IGF2, and MLH1 (data not shown)." (PMID 20027224, 2009). "Even though the microsatellite study pointed to loss of heterozygosity rather than complete loss of the region containing CDKN2A and CDKN2B, no PCR products could be obtained from the tumour for the genes themselves, except for CDKN2A exon 1β." (PMID 19643034, 2009). "The expression level of CDKN2A was determined using quantitative real-time RT-PCR, and the three samples with deletion of the region showed no or very low expression compared to the benign tumors, whereas the other three samples showed increased expression." (PMID 18522746, 2008). "For example, the promoter regions of genes such as PIK3CA and cyclin-dependent kinase inhibitor 2A (CDKN2A) show high levels of methylation in EBVaGC, which not only affects the expression of these genes but may also reduce metastatic potential by inhibiting tumor stemness." (PMID 41573653, 2025). "Interestingly, when using an assay targeting all CDKN2a transcripts, i.e. both p16INK4a and p14ARF mRNA, the expression levels increased in a stepwise fashion when comparing control mucosa, non-cancerous mucosa and tumor tissue." (PMID 40357388, 2025). "These mutations may occur in receptors (e.g., KITKIT), effectors (BRAF, NRAS), or inhibitors (NF1, RASA2, CDKN2A, SPRED1) of the pathway, leading to proliferation of transformed melanocytes, abnormal differentiation, and persistent survival with impaired apoptosis of tumour cells." (PMID 41295253, 2025). "Specifically for this patient, the following were discussed: firstly, there was still a remnant tumor in an eloquent region of the brain; next, the Ki-67 index was 5%; and lastly, the molecular findings of an NTRK gene fusion included the lack of BRAFV600E mutation and CDKN2A homozygous deletion." (PMID 39108689, 2024). "Next, we asked if CDKN2A alteration could affect other immune components; therefore, we checked the correlation of CDKN2A alteration with the chemokine CCL4 and the chemokine receptor CCR6, which are known for their immunosuppressive roles against tumor development." (PMID 37626750, 2023). "These non-malignant cells may mask CDKN2A gene HD that are only present in tumor cells." (PMID 34249754, 2021). "Thus, it is possible that in the context of certain tumor types such as those studied here, the decreased expression of SASP factors observed upon p16 knockdown or in CDKN2A-low patients may contribute to abrogation of senescence surveillance by immune cells, thereby promoting tumorigenesis." (PMID 33550279, 2021).
tumor (continued). "Thus, C-MET, CDKN2A, P-glyc (ABCB1) and N-cadherin displayed significantly lower protein expression levels in HGSOC tumors corresponding to PARPis-sensitive AsPCs, while FANCF and SPRY2 showed stronger expression in the PARPis-sensitive AsPCs-matched tumor samples." (PMID 33213473, 2020). "Although other tumor suppressors may also be repressed by the PRC1 complex in the process of tumorigenesis, the oncogenic function of BMI1 and other PRC1 components has been mainly attributed to their repression of the cyclin-dependent kinase inhibitor 2A (CDKN2A) locus." (PMID 31211140, 2019). "However, we found that the tumor sample of 033 T patient diagnosed as poorly differentiated metastatic lung adenocarcinoma, PDXs, and PDX cells exhibited focal MET and HER2 co-amplification and CDKN2A deletion without a known RTK/RAS/RAF activating mutation." (PMID 28806950, 2017). "In contrast, mutations and CN alterations affecting cell cycle regulators, such as MYCN, CDK4 and CDKN2A/B, except for MDM2, were particularly enriched in the A1/A2 clusters compared with the E1/E2 clusters (P=0.016), suggesting that these genes may have driver roles in A1/A2 tumours." (PMID 26138366, 2015). "Of the seven AA3 tumors, three contained EGFR amplification with monosomy 10 or CDKN2A/B deletion, a pattern more typical of GBM than ALGG suggesting that these tumors may in fact be more clinically aggressive than typical AA3s or under-sampled with respect to the overall features of the tumor." (PMID 25257301, 2014). "However, the non-negligible methylation occurring in the adjacent normal colorectal mucosa may confound the assessment of tumor-specific CDKN2A hypermethylation suggesting that corresponding non-neoplastic tissue should be used as a control." (PMID 22925370, 2012). "Nevertheless, we see how molecular phenotypes can segregate in overall survival, with certain tumor clusters, such as those without ATRX alteration, having a median survival of over three times that of tumors with CDKN2A/B alteration." (PMID 39584448, 2025). "Conversely, among the 12 cases lacking CDKN2A HD, cytoplasmic expression of MTAP in at least 1% of tumour cells was observed in 9 cases, whereas 3 resulted completely negative." (PMID 40566743, 2025). "Additional amplification of WT1, ERC1, ASIC2 and MTCP1 and deletion of CDKN2A and MLLT3 were found in recurring MFS (case 8b) but not in the original tumor (case 8a)." (PMID 38791144, 2024). "In some cells and tumours, insensitivity is predicted by the absence of active T172‐phosphorylated CDK4, mostly due to elevated p16/CDKN2A levels consequent to defects or cyclin E‐dependent inactivation of pRb." (PMID 36453028, 2024). "The aim of the study was to investigate the methylation status of CDKN1, CDKN2A, MYC, Smad3, SP1, and UBC genes in tumor tissue (control-normal tissue) in 50 patients (37 men and 13 women) with HPV-negative HNSCC." (PMID 38540340, 2024). "For example, CDKN2A positively correlates with RNAss and DNAss in LIHC, while it showed a significantly negative correlation with tumor stemness in TGCT and KIRP." (PMID 36647100, 2023). "In one case with a homozygous deletion of both CDKN2A and MTAP and one case with a homozygous CDKN2A deletion and heterozygous MTAP deletion, strong MTAP expression was seen in 10% of the tumor cells, whereas p16 was negative in both cases." (PMID 37894345, 2023).
tumor (continued). "CDKN2A and CDKN2B deletions were found in the MPM665 patient-derived cell line but not in the corresponding tumor." (PMID 37345150, 2023). "Cell proliferation, colony formation and tumor sphere formation were inhibited by silencing the expression of circMET compared with the negative control in UOK109 cells, but the knockdown of CDKN2A reversed this phenomenon." (PMID 35042525, 2022). "In summary, we have not demonstrated that a change in expression profiles of CDKN2A, MDM2, E2F2 and LTF genes in tumour and margin tissues has a significant impact on the pathogenesis of OSCC." (PMID 36551770, 2022). "For the CD7 xenograft, we did not observe any tumor growth response to both palbociclib and volasertib (p = 0.85 and p > 0.99, respectively), as well as for the CD39 xenograft without CDKN2A/2B deletion (p = 0.40 and 0.058, respectively)." (PMID 36505864, 2022). "Nevertheless, CDKN2A is not directly involved in DDR; rather, its main products, p16INK4a and p14ARF, are tumor suppressors involved in cell cycle regulation." (PMID 34034685, 2021). "The Cancer Panel identified MET amplification and CDKN2A deletion in 033 T sample and HER2 was amplified in the PDXs and PDX cells but not in the patient tumor sample." (PMID 28806950, 2017). "Unlike hypermethylated gastric CpG island methylator phenotype tumours, no GEA-CIN tumours exhibited epigenetic silencing of MLH1, consistent with their MSI-negative status, but they showed a higher propensity for epigenetic silencing of CDKN2A." (PMID 28052061, 2017). "The similar phenomenon was observed in large number of tumors in other tumor types, such as GBM and HNSC, where the CDKN2A was overexpressed in almost all tumors without CDKN2A amplifications." (PMID 26317392, 2015). "Other clinico-pathological factors, including tumor location, did not affect the prognostic role of concurrent methylation in NEUROG1 and CDKN2A (p16)." (PMID 26157509, 2015). "In our study, the genes CDKN2B, CDKN2A, and RB1 were not methylated and hipoexpressed in all the tumor grades analyzed." (PMID 26317630, 2015). "Whole exome sequencing of tumor obtained at time of progressive disease did not reveal secondary BRAF or RAS mutations, but did demonstrate a somatic gain-of-function PIK3CA mutation (H1047R) as well as a CDKN2A aberration, which may have been responsible for dabrafenib resistance." (PMID 23470635, 2013). "CDKN2B's neighbor, cyclin-dependent kinase inhibitor 2A (CDKN2A), functions similarly to inhibit Cdk4 and is a known tumor suppressor, but is not detectably expressed in either normal or tumor tissue." (PMID 20174472, 2010). "For example, unlike many current tumor markers, such as CA19-9, CA125 and PSA, which are not truly cancer-specific, the CDKN2A breakpoints are specific and unique for each cancer with this locus deleted." (PMID 17440616, 2007). "No significant change was detected for CDKN2A/p16INK4a, CDKN2A/p14ARF,CDKN2B/p15INK4b, MTAP, IFNA and IFNB mRNAs in tumours with 9p21–23 LOH when compared to those with retained heterozygosity." (PMID 15305192, 2004).